TUBA1A (tubulin alpha 1a)
Diseases named in the same sentence as TUBA1A in open-access papers (continued):
Sharing a sentence is not in itself a finding about the gene and the disease.
tubulinopathies (continued). "Patients presenting with hypotonia, macrocephaly, and hypoplastic genitalia as well as brain malformations and seizures may not have WWS and should be considered for genetic testing for a possible tubulinopathy particularly involving the TUBA1A gene." (PMID 39202391, 2024). "Based off our work and that of others, there does not appear to be a consistent mechanism for how TUBA1A tubulinopathy mutations affect microtubule networks and neuron cell biology." (PMID 35511030, 2022). "TUBA1A tubulinopathy shows a more severe clinical and neuroradiological phenotype than β-tubulinopathies comprising a combination of MCDs and changes of extra-cortical structures such as cerebellum, corpus callosum (CC), basal ganglia, brainstem, and ventricles." (PMID 35017693, 2022). "Cortical malformations and neuronal migration errors are also common features of TUBA1A tubulinopathies; however, it has thus far been unclear whether commissural deficits occur as a primary or secondary consequence of TUBA1A dysfunction." (PMID 35127710, 2021). "Additionally, abnormalities of corpus callosum (CC) were significantly more common in TUBA1A tubulinopathy (96.1% vs. 77.5%; P < 0.001)." (PMID 33082561, 2021). "The present case resembles TUBA1A-associated tubulinopathy, rather than classic TUBB3 CFEOM3, where nystagmus was present in 3/29 (10.3%) cases, and no CFEOM phenotypes were observed." (PMID 33921132, 2021). "Despite our effort to collect all variants and clinical information described for TUBA1A-associated tubulinopathy, we did not obtain enough data to further analyze the phenotype differences for these variants." (PMID 30744660, 2019). "In recent years, an increasing number of tubulin genes were linked to a clinically heterogeneous group of disorders, the “tubulinopathies” (TUBA1A, MIM#602529; TUBA8, MIM#605742; TUBB2A, MIM#615101; TUBB2B, MIM#612850; TUBB3, MIM#602661; TUBB, MIM#191130; TUBG1, MIM#191135)." (PMID 30744660, 2019). "Quantitative natural history modeling of individuals with TUBA1A and TUBB2B tubulinopathies from clinical reports and database entries of DECIPHER and ClinVar." (PMID 33082561, 2021). "Epilepsy is a cardinal feature at disease onset of TUBA1A and TUBB2B tubulinopathy: 65.9% and 54.8% of patients, respectively, developed seizures during the observation period." (PMID 33082561, 2021). "In this present study, we define the important primary endpoints survival, disease onset, and diagnostic delay analyzing the so-far largest quantitative analysis cohort of patients with TUBA1A and TUBB2B tubulinopathy." (PMID 33082561, 2021). "During the course of disease, motor impairment, developmental delay, abnormalities of the muscular tone, microcephaly, and epilepsy were the most frequent clinical features but differed in distribution between individuals with TUBA1A and TUBB2B tubulinopathy." (PMID 33082561, 2021). "TUBA1A and TUBB2B tubulinopathies are rare neurodevelopmental disorders characterized by cortical and extracortical malformations and heterogenic phenotypes." (PMID 33082561, 2021). "TUBA1A and TUBB2B tubulinopathies usually become symptomatic in infancy at an average age of 4 and 6 months, respectively, but a considerable diagnostic delay of 4.2 and 12.3 years is observed until a genetic diagnosis is established." (PMID 33082561, 2021). "We quantitatively and comparatively delineate the natural history of TUBA1A and TUBB2B tubulinopathies by assessment of a large meta-cohort of 203 patients and provide their distinctive clinical features." (PMID 33082561, 2021). "Another distinct feature that has not previously been described in TUBA1A tubulinopathy was ischemia in the territory of the posterior cerebral arteries in both cases." (PMID 35017693, 2022).
tubulinopathies (continued). "If haploinsufficiency does not explain all TUBA1A tubulinopathies, then it is necessary to define clear mechanistic models for how different mutations in α-tubulin can result in different developmental outcomes." (PMID 35511030, 2022). "Here we harness a previously-identified internal loop within TUBA1A that tolerates addition of small epitope tags without impacting TUBA1A incorporation or dynamics to generate an important tool for the study of tubulinopathies and neuronal α-tubulin." (PMID 35127710, 2021). "Moreover, we sharpen the phenotypic profile of TUBA1A and TUBB2B tubulinopathy by comprehensively delineating isotype-dependent characteristics at disease onset and in the course of disease as well as neuroradiological features associated with epilepsy and an unfavorable clinical outcome." (PMID 33082561, 2021).
microcephaly (21 papers, 2014 to 2024). A congenital or acquired developmental disorder in which the circumference of the head is smaller than normal for the person's age and sex. "In the context of fission yeast, this substitution blocks the ability of human γ-tubulin to complement deletion of endogenous (S. pombe) γ-tubulin while A174V in TUBA1A is associated with microcephaly." (PMID 38064432, 2023). "The association between microcephaly, polymicrogyria and cerebellar agenesis prompted us to screen for tubulin genes (TUBA1A, TUBA8, TUBB2A, TUBB2B, TUBB3, TUBB4A, TUBB, TUBG1), which were all negative." (PMID 35162247, 2022). "Early postnatal symptoms in individuals with TUBA1A variants were most frequently microcephaly (54.3%), seizures (42.9%), and muscular hypotonia (37.1%)." (PMID 33082561, 2021). "Tubulin-beta forms a dimer with tubulin-alpha, encoded by TUBA1A, a gene mutated in syndromic cortical malformation with microcephaly, cerebral and cerebellar dysgyria." (PMID 28542170, 2017). "Mutations of TUBA1A in this gene cause lissencephaly type 3 (LIS3), a neurological condition characterized by microcephaly, mental retardation, early-onset epilepsy, and defective neuronal migration." (PMID 25295026, 2014). "Several de novo mutations have also been identified in other genes mutated in microcephaly (i.e. CTNNB1 and TUBA1A) and in primary lymphedema, such as SOX18, FOXC2 and VEGFR3." (PMID 25934493, 2015). "Subsequent WES analysis revealed a novel heterozygous likely pathogenic TUBA1A missense variant in the affected sibling, presenting with severe intellectual disability and microcephaly, which was absent from the non-affected sibling." (PMID 36672823, 2022). "Interestingly, we found several differentially expressed genes following infection with ZIKV Uganda, including COL4A1, MIR17HG, TUBA1A, SLC2A1 and STAMBP, which are associated with microcephaly according to the comparative toxicogenomics database." (PMID 33121145, 2020). "Microtubule structure alterations as well as alterations of binding partners necessary for proper microtubule dynamics resulting from pathogenic variants in TUBA1A, TUBB2A, TUBB2B, TUBB3, TUBB5, TUBG1 and TUBA8 genes are also responsible microcephaly and microlissencephaly." (PMID 30340542, 2018). "As TUBA1A is not expressed in neuronal progenitors, microcephaly associated with TUBA1A likely fits into the secondary microcephaly classification." (PMID 29057214, 2017).
brain malformations (16 papers, 2015 to 2025). "In this study, we aim to determine the mechanism of two different substitutions at the valine 409 residue of TUBA1A that are associated with different severities of brain malformations." (PMID 35511030, 2022). "Together, our results suggest that the TUBA1A-V409I/A mutations cause brain malformations by subverting dynamic regulation typically conferred by XMAP215." (PMID 35511030, 2022). "In this study, we identified three de novo missense variants in TUBA1A in three individuals with global developmental delay and brain malformations." (PMID 30744660, 2019). "Mutations in TUBA1A have been reported in patients with a range of brain malformations, including lissencephaly, microlissencephaly, polymicrogyria, and simplified gyri." (PMID 30087272, 2018). "Brain malformation-causing TUBA1A mutations provide an irreplaceable opportunity to explore the role of microtubules at the cellular level of neuronal maturation, and at the tissue level of brain formation." (PMID 29057214, 2017). "TUBA1A mutations may disrupt neuronal migration, are associated with brain malformations, and are characteristic of familial recurrence, indicating that TUBA1A mutations may result in IS." (PMID 38041198, 2023). "However, TUBA1A mutations remain the most common cause of tubulin-related brain malformations, with over 60 mutations being described to date." (PMID 30087272, 2018). "TUBA1A was the first tubulin gene to be associated with human brain malformations." (PMID 30087272, 2018). "Mutations in TUBA1A have been reported to cause a range of brain malformations." (PMID 30087272, 2018). "The wide variety of brain malformations observed in patients leads to the prediction that different missense mutations in TUBA1A may disrupt different neuronal maturation phases." (PMID 29057214, 2017). "We will particularly focus on TUBA1A, discussing its regulated expression, mutations associated with brain malformations, and how this α-tubulin might uniquely contribute to normal brain development." (PMID 29057214, 2017). "Therefore, many of the reported TUBA1A mutations at positions associated with lateral interactions caused severe phenotypes of brain malformations (LCH severe group 4)." (PMID 26493046, 2015). "In conclusion, our data suggest that mutations in TUBA1A at positions essential for lateral interactions may lead to severe phenotypes of brain malformations." (PMID 26493046, 2015). "The brain MRI of our patient harbouring the TUBA1A p.R64W mutation manifested an extremely thin cerebral parenchyma with severe hydrocephalus, agenesis of the cerebellum and the corpus callosum, and hypoplastic brain stem, the most severe form of brain malformations." (PMID 26493046, 2015). "In the probands with brain malformation, which was most common phenotype in our cohort, TUBA1A was the most frequently observed gene, identified in 12 probands, including one possessing both the TUBA1A and SCN8A pathogenic variants." (PMID 39433808, 2024). "Strikingly, TUBA1A-V409I presents an intermediate phenotype between WT and TUBA1A-V409A in each assay we tested, tracking with the observed brain malformations observed in these patients." (PMID 35511030, 2022). "According to earlier research, overexpression of TUBA1A may disrupt the activities of the cytoskeleton and cell junctions, resulting in congenital cataracts, microphthalmia, and brain malformations." (PMID 39160465, 2024). "Thus, our data indicate that the spectrum of TUBA1A-related brain malformations is broader than expected." (PMID 26493046, 2015). "Without these characteristics, it is difficult to determine whether a case with certain brain malformations is a TUBA1A-related disorder using only MRI findings." (PMID 26493046, 2015).
Pachygyria (11 papers, 2007 to 2023). Pachygyria is a malformation of cortical development with abnormally wide gyri with sulci 1,5-3 cm apart and abnormally thick cortex measuring more than 5 mm (radiological definition). "For instance, p.R264C mutation occurs frequently in the TUBA1A patient population (12.5%), causes the less severe pachygyria phenotype, and is one of the most investigated mutations." (PMID 29057214, 2017).
polymicrogyria (10 papers, 2014 to 2024). A developmental brain abnormality characterized by an excessive amount of small convolutions on the surface of the brain and cognitive dysfunction. "Interestingly, mice Tuba1a (p.I5F) has an OrthoVar (p.I5L) in human TUBA1A, and the human TUBA1A(p.I5L) variant is implicated in a condition called polymicrogyria." (PMID 36700112, 2021).
epilepsy (8 papers, 2007 to 2025). A brain disorder characterized by episodes of abnormally increased neuronal discharge resulting in transient episodes of sensory or motor neurological dysfunction, or psychic dysfunction. "TUBA1A-associated epilepsy shows various semiologies and predominantly manifests in the first year of life, which is supported by the results in our study." (PMID 35017693, 2022). "Among patients described in literature carrying mutations in TUBA1A gene, epilepsy was reported in 28% (44/155), while it was described in 49% (19/39) of TUBB2B and in 5% (3/62) of TUBB3 mutated patients." (PMID 31269740, 2019). "Pathogenic variants in TUBA1A have been shown to cause a neurodevelopmental syndrome, characterized by structural brain malformations, congenital microcephaly, developmental delay, intellectual disability, and epilepsy (OMIM: 611603)." (PMID 39495751, 2024). "Individuals generally showed a broad range of focal and generalized semiologies that occurred similarly in TUBA1A- and TUBB2B-associated epilepsy." (PMID 33082561, 2021). "Epilepsy was common in both cohorts: 65.9% (TUBA1A) and 54.8% (TUBB2B) of individuals developed seizures during the observation period." (PMID 33082561, 2021). "Among the α- and β-tubulin genes, TUBA1A (28% of the cases) and TUBB2B gene (49%) are those more frequently associated with epilepsy." (PMID 31269740, 2019). "Incidence of mutations associated with epilepsy is not significantly different among the tubulin domains for TUBA1A and TUBB2B genes, while in the TUBB3 gene, the C-domain does not show mutations related to epileptic features." (PMID 31269740, 2019). "EEG and clinical data of six epileptic patients from a cohort of 15 patients carrying mutations in TUBA1A, TUBB2B and TUBB3 tubulin genes are analyzed as well as a literature review on the role of these genes and epilepsy is reported with the aim to define a specific associated epileptic pattern." (PMID 31269740, 2019). "Mutations in TUBA1A (60%) and TUBB2B (74%) and TUBB3 (25%) genes are associated with epilepsy." (PMID 31269740, 2019). "Clinical and EEG data: six out of 15 patients presented epileptic seizures (40%) (three with TUBA1A gene mutation and three with TUBB2B gene mutation; none TUBB3 carrying gene mutation showed epilepsy)." (PMID 31269740, 2019).
microlissencephaly (7 papers, 2014 to 2025). Microlissencephaly describes a heterogenous group of a rare cortical malformations characterized by lissencephaly in combination with severe congenital microcephaly, presenting with spasticity, severe developmental delay, and seizures and with survival varying from days to years. "Conversely, sporadic cases have barely been reported while they represent at least 40% of our foetal cohort, and we have been able to provide evidence here that TUBA1A mutations are a major cause of microlissencephaly, accounting for 46.4% of our cases." (PMID 25059107, 2014). "Most patients with microlissencephaly (10/13) carried mutations in TUBA1A gene." (PMID 25059107, 2014). "In this cohort, TUBA1A mutations represent the major cause of microlissencephaly, although TUBB2B and TUBB3 mutations may also be found." (PMID 25059107, 2014). "Because of the potential implications for the genetic screening, our data together with these observations imply that microlissencephaly must be distinguished from LCH, the former being related to either TUBA1A, TUBB2B or TUBB3 mutations, while the latter strongly related to TUBA1A mutations." (PMID 25059107, 2014).
cervical cancer (5 papers, 2020 to 2024). A primary or metastatic malignant neoplasm involving the cervix. "There is evidence indicating that the lncRNA FENDRR/miR-15b-5p/TUBA1A axis suppresses cervical cancer cell proliferation and invasion 48, and the lncRNA TTN-AS1 suppresses ovarian cancer cell proliferation and invasion by targeting miR-15b-5p and regulating FBXW7 expression." (PMID 38911389, 2024). "One study demonstrated that FENDRR could inhibit cervical cancer proliferation and invasion by targeting miR-15a/b-5p and regulating TUBA1A expression." (PMID 38200098, 2024). "In cervical cancer, FENDRR acts as a ceRNA, inhibiting tumor progression by upregulating tubulin alpha1A (TUBA1A) in a miR-15a/b-5p-dependent manner." (PMID 34621665, 2021).
breast carcinoma (4 papers, 2021 to 2025). "According to a bioinformatic study, the expression of the genes FLRT2, SLIT2, VNN1, MAP1B, MYLK, and TUBA1A was found to be higher in normal tissue than in malignant tissue in patients with breast cancer." (PMID 39596804, 2024). "Bioinformatic analysis indicated that FLERT2, SLIT2, VNN1, MAP1B, MYLK, and TUBA1A gene expressions were found to be higher in normal tissue than in tumor tissue of breast cancer patients." (PMID 39596804, 2024). "This aggressive phenotype overexpressing TUBA1A was reported in the paclitaxel-resistant MCF7 breast cancer cell line." (PMID 39596804, 2024). "Two proteins linked to the dynamics of the microtubule cytoskeleton, MAP1B and TUBA1A, were found to have unfavorable effects on patients with breast cancer when their expression levels were high in this study." (PMID 39596804, 2024). "In this study, we used a breast cancer model to examine the effects of radiation alone or in combination with estrogens on the expression of genes linked to cell motility, such as ADAM12, CYR61, FLRT2, SLIT2, VNN1, MYLK, MAP1B, and TUBA1A." (PMID 39596804, 2024). "Lastly, the survival of breast cancer patients was significantly influenced by the high expression of TUBA1A in Luminal B patients and MAP1B in Luminal A patients, which corroborated the importance of these markers and the expression of genes and proteins related to cell motility." (PMID 39596804, 2024). "In addition, THRAP3, TARDBP, and YY1 were the most stably expressed genes in the breast cancer cell lines, while B2M, TUBA1A, and ACTB were the least stably expressed genes." (PMID 34895237, 2021). "In the breast cancer cell group THRAP3, RHOA, and QRICH1 were the top three stably expressed genes, while B2M, TUBA1A, and ACTB were the least stably expressed genes." (PMID 34895237, 2021). "For all breast cancer tissue and cell line samples, THRAP3, RHOA, QRICH1 were the most stably expressed genes, and TUBA1A, B2M, ACTB were the least stably expressed RGs." (PMID 34895237, 2021). "In the breast cancer cell group, THRAP3, DNAJC8, and RPL13A were the three most stably expressed genes, while TUBA1A, B2M, and ACTB were the least stably expressed genes." (PMID 34895237, 2021). "In the breast cancer cell line group, THRAP3, RHOA, and QRICH1 were the three most stably expressed genes, while B2M, ACTB, and TUBA1A were the least stably expressed genes." (PMID 34895237, 2021). "In addition, GUSB, TUBA1A, RPL13A, and B2M, which previous studies suggested being stable RGs in breast cancer research, and two classical RGs, ACTB and GAPDH, were also considered." (PMID 34895237, 2021). "In previous breast cancer studies, commonly used RGs included beta-actin (ACTB), glyceraldehyde-3-phosphate dehydrogenase (GAPDH), beta-glucuronidase (GUSB), ribosomal protein L13a (RPL13A), and tubulin alpha 1a (TUBA1A)." (PMID 34895237, 2021).
developmental delay (4 papers, 2017 to 2024). "Using exome analysis in three unrelated individuals with severe developmental delay we identified three heterozygous de novo missense variants in the TUBA1A gene." (PMID 30744660, 2019). "In three individuals with developmental delay we identified heterozygous de novo missense variants in TUBA1A using exome sequencing." (PMID 30744660, 2019).